DSG2 (desmoglein 2)
Diseases named in the same sentence as DSG2 in open-access papers (continued):
Sharing a sentence is not in itself a finding about the gene and the disease.
colon carcinoma (continued). "This peptide targets the DSG2 cell adhesion recognition (CAR) domain and has been previously demonstrated to block DSG2-mediated alveolar morphogenesis by epithelial cells and colon carcinoma cell aggregation." (PMID 27340778, 2016).
melanoma (20 papers, 2010 to 2025). A malignant, usually aggressive tumor composed of atypical, neoplastic melanocytes. "Of relevance here, DSG2 is an important regulator of both angiogenesis and VM; for example, in a mouse model of melanoma, loss of Dsg2 expression in the host was associated with fewer EC-lined tumor vessels." (PMID 38188287, 2023). "In patient-derived melanoma cell lines and tumor tissues, the overexpression of DSG2 was associated with poor clinical outcome primarily because DSG2 can promote vasculogenic mimicry activity in human melanoma cells." (PMID 36016457, 2022). "We found that DSG2 overexpression in human melanoma is associated with enhanced VM, increased expression of VM-associated genes and reduced progression-free and overall survival." (PMID 27340778, 2016). "The biological function of DSG2 in melanoma remains poorly defined, although one study has linked its expression to the regulation of melanoma cell motility." (PMID 27340778, 2016). "Loss of desmoglein 2 increases expression of secretogranin II, followed by an enhanced migratory activity of melanoma cells." (PMID 24558503, 2014). "Interestingly, it should be noted that MX2 overexpression also led to a significant decrease of DSG2 expression which has previously been associated with unfavorable melanoma outcome." (PMID 33734579, 2021). "Recent studies have shown that the expression of DSG2 in human melanoma is associated with VM." (PMID 32997416, 2020). "Thus, melanoma cells expressing high levels of DSG2 also express elevated levels of VM-associated genes, suggesting that DSG2 is part of a broader genetic program which regulates VM in tumors." (PMID 27340778, 2016). "Furthermore, analysis of TCGA data revealed that melanomas overexpressing DSG2 are also enriched in genes associated with embryogenesis." (PMID 27340778, 2016). "Thus, DSG2 overexpression is associated with increased VM in human melanoma." (PMID 27340778, 2016). "Blocking trans interaction between DSG2 and Siglec‐9 significantly enhances macrophage phagocytosis of melanoma cells, presenting sialylated DSG2 as a potential target in cancer immunotherapy." (PMID 39813162, 2025). "Here, proximity labeling combined with genetic screening to identify DSG2 as a dominant counter receptor of Siglec‐9 in melanoma." (PMID 39813162, 2025). "DSG2 was overexpressed 14.5-fold in case 2 and also enables vasculogenic mimicry a mechanism by which melanoma cells increase their blood supply and are directly connected to the circulation, permitting vascular invasion." (PMID 40717170, 2025). "Here, the identification of DSG2 (Desmoglein 2) as a dominant counter receptor of Siglec‐9 in melanoma cells is reported, using a workflow that combines the strength of proximity labeling and the advantage of CRISPR knockout screening." (PMID 39813162, 2025). "We successfully discovered Desmoglein 2 (DSG2) as a functionally important counter receptor for Siglec‐9 in human melanoma cell line A375." (PMID 39813162, 2025). "Dsg2 is often overexpressed in cancers, including NMSC, and is associated with poor prognosis in melanoma as it promotes tumor angiogenesis." (PMID 38473864, 2024). "On the other hand, we have previously shown that DSG2 contributes to homotypic cell–cell adhesion between melanoma cells and endothelial cells, both of which lack classical desmosomal structures." (PMID 34245117, 2022). "Dsg2 depletion also increases the expression of migration-related genes such as secretogranin II, which enhanced the migratory activity of melanoma cells." (PMID 34168237, 2021). "Several previous studies have also demonstrated that DSG2 is highly expressed in several tumors, such as gastric cancer, skin squamous cell carcinomas, and melanoma." (PMID 33217893, 2020). "Recently, some scholars have confirmed that the expression of DSG2 in human melanoma is related to the role of tumor VM." (PMID 32997416, 2020).
melanoma (continued). "Several investigators reported high DSG2 expression in melanomas, human epithelial squamous cell cancer, basal cell cancer, non-small cell lung cancer, and colonic adenocarcinoma." (PMID 32300605, 2020). "To better understand the frequency of DSG2 expression on cultured melanoma cells, we performed gene expression microarray analysis on a panel of 28 human melanoma cell lines." (PMID 27340778, 2016). "Compared to normal melanocytes, DSG2 was overexpressed in a substantial fraction of human melanoma tissues and cell lines, and its expression in patient tumors was associated with enhanced VM, an enrichment of VM-associated genes and reduced overall survival." (PMID 27340778, 2016). "DSG2+ melanoma cells self-organized into tube-like structures on Matrigel, indicative of VM activity, which was inhibited by DSG2 knockdown or treatment with a DSG2-blocking peptide." (PMID 27340778, 2016). "We found that DSG2 is expressed at high levels by ES cells and down-regulated upon differentiation to mature melanocytes, but then re-expressed in a subset of melanomas." (PMID 27340778, 2016). "To resolve this, we undertook a comprehensive analysis of DSG2 expression in a large number of patient melanomas using two different anti-DSG2 mAbs." (PMID 27340778, 2016). "Analysis of patient-derived melanoma cell lines and tumor tissues, and interrogation of The Cancer Genome Atlas (TCGA) data, revealed that DSG2 is frequently overexpressed in primary and metastatic melanomas compared to normal melanocytes." (PMID 27340778, 2016). "Strikingly, despite the plethora of adhesion molecules expressed on melanoma cells, reducing expression of just DSG2 produced a significant reduction in cell-cell adhesion (p < 0.01)." (PMID 27340778, 2016). "In contrast, expression of other desmosomal cadherins (DSG1, DSG3, DSC1, DSC2, DSC3) was negligible, revealing that DSG2 is unique within this gene family for its expression in a large proportion of melanoma cell lines." (PMID 27340778, 2016). "Our mechanistic studies using cell lines revealed an important role for DSG2 in promoting melanoma cell tube formation on Matrigel, an in vitro correlate of VM." (PMID 27340778, 2016). "Additional studies are warranted to further explore the importance of DSG2-induced VM to melanoma pathogenesis, and to evaluate this molecule as a new therapeutic target in melanoma." (PMID 27340778, 2016). "We therefore next assessed a potential link between DSG2 expression and VM occurrence in patient melanomas." (PMID 27340778, 2016). "On the other hand, DSG2 knockdown did significantly reduce the ability of melanoma cells to adhere to each other, suggesting that DSG2 promotes VM by mediating intercellular adhesion, presumably in a non-desmosomal context." (PMID 27340778, 2016). "The results presented thus far demonstrate that DSG2 is overexpressed in a large fraction of melanomas compared to normal melanocytes, and that this overexpression is associated with poor clinical outcome." (PMID 27340778, 2016). "We therefore propose that DSG2 expression is induced in melanoma as part of a genetic program resulting in re-expression of embryonic genes, endowing cells with the functional plasticity required to undergo VM." (PMID 27340778, 2016). "In summary, our observations reveal DSG2 as a novel regulator of VM in human melanoma and a marker of prognostic significance in this disease." (PMID 27340778, 2016). "It was therefore important to determine the precise activity which DSG2 controls in melanoma cells during tube formation." (PMID 27340778, 2016). "When the same tumors were labelled with antibodies to Dsg2, all primary melanomas and 7 of 8 melanoma metastases exhibited rather diffuse Dsg2-positive immunoreactions within the cytoplasm and/or at the cell surface of the tumor cells." (PMID 24558503, 2014). "The aim of this study was to analyze the impact of Dsg2 on tumorigenic properties of melanoma cells." (PMID 24558503, 2014).
melanoma (continued). "Concentration of Dsg2 at cell boundaries was observed only rarely and only focally in small clusters of melanoma cells." (PMID 24558503, 2014). "Our data add a new pathway of regulating melanoma cell migration related to a desmoglein 2 – secretogranin II axis." (PMID 24558503, 2014). "Our study provides evidence that depletion of Dsg2 leads to increased migration of melanoma cells rich in endogenous Dsg2." (PMID 24558503, 2014). "We have detected Dsg2 in two of eight melanoma cell lines in culture and in a subset of human melanomas and metastases." (PMID 24558503, 2014). "In the majority of primary melanomas and melanoma metastases analyzed here we noted rather diffuse Dsg2 immunoreactions in the cytoplasm and/or on the cell surface." (PMID 24558503, 2014). "In cultured melanoma cells Dsg2 is distributed diffusely on the cell surface, as previously demonstrated by confocal laser scanning and immunoelectron microscopy." (PMID 24558503, 2014). "We have previously shown that certain melanoma cell lines express, in addition to classical cadherins, the desmosomal cadherin desmoglein 2 (Dsg2)." (PMID 24558503, 2014). "Transwell invasion assays showed appreciably increased invasion of melanoma cells upon Dsg2 depletion." (PMID 24558503, 2014). "In conclusion our data add a new pathway of regulating melanoma cell migration related to a newly described Dsg2 – SgII axis." (PMID 24558503, 2014). "How exactly the cell surface expression of Dsg2 is modulated in melanoma cells and how the protein alters adhesion of these cells remains to be studied." (PMID 24558503, 2014). "In Matrigel-coated Transwell assays we additionally documented increased invasion of Dsg2-depleted melanoma cells." (PMID 24558503, 2014). "Of course localization patterns detected by immunostaining strongly depend on the methods and reagents applied, and of course occurrence of Dsg2 in melanomas in vivo will have to be confirmed by different techniques including quantitative PCR and Western blot." (PMID 24558503, 2014). "Importantly, blocking trans interaction between DSG2 and Siglec‐9 significantly enhances macrophage phagocytosis of melanoma cells and, to a lesser extent, other cancer cells." (PMID 39813162, 2025). "We have also demonstrated that the trans interaction between DSG2 on A375 melanoma cells and Siglec‐9 on macrophages has a significant impact on the Siglec‐9‐mediated immunosuppressive signaling and knocking down DSG2 releases immunosuppression and increases phagocytosis." (PMID 39813162, 2025). "Our findings thus suggest that DSG2 may function as a “don't eat me” signal in melanoma, warranting further investigation." (PMID 39813162, 2025). "Given the specific interaction of DSG2 with Siglec‐9 in A375 cells, the function of DSG2 in melanoma could be related to Siglec‐9 and its immunosuppressive signaling in immune cells." (PMID 39813162, 2025). "While further studies are required to fully elucidate the role of DSG2 in VM formation, data to-date suggest that targeting DSG2 in melanoma may inhibit VM formation and suppress tumor growth and metastasis." (PMID 38188287, 2023). "Furthermore, elevated DSG2 on melanoma cells promoted the formation of VM structures in vitro; in support of a pro-vascular phenotype, melanoma cancer cells expressing high levels of DSG2 also overexpress VM-associated genes." (PMID 38188287, 2023). "DSG2 also served as a poor prognostic indicator in melanoma." (PMID 32300605, 2020). "Analysis of primary (stage I/II; n = 46) and metastatic (stage III/IV n = 25) tumors revealed DSG2 expression by S100+ melanoma cells in 39% of primary tumors and 24% of metastatic tumors, which was not a statistically significant difference (p = 0.294, Fisher's Exact test)." (PMID 27340778, 2016). "We thus assessed the effect of DSG2 inhibition on these parameters in melanoma cells, to determine whether they could contribute to the observed reduction in tube formation." (PMID 27340778, 2016).
melanoma (continued). "In a previous study, DSG2 expression was detected in 2/8 melanoma cell lines." (PMID 27340778, 2016). "Here, we reveal the adhesion molecule desmoglein 2 (DSG2) as a novel mediator of VM in melanoma." (PMID 27340778, 2016). "Here, we demonstrate that DSG2 fulfils a related function in melanoma, by promoting VM." (PMID 27340778, 2016). "Here, we reveal that DSG2 plays an analogous, cell-intrinsic role in melanoma by regulating VM." (PMID 27340778, 2016). "Here, we have identified DSG2 as a novel regulator of VM in human melanoma." (PMID 27340778, 2016). "We therefore hypothesized that DSG2 regulates at least one aspect of melanoma cell biology that contributes to tumor growth or spread." (PMID 27340778, 2016). "On the basis of these findings, we propose that DSG2 is induced during tumorigenesis in a large subset of melanoma patients and functions to promote the formation of VM networks, which in turn may help drive tumor growth and progression." (PMID 27340778, 2016). "Finally, we performed differential gene expression analysis of TCGA data to identify genes overexpressed in DSG2-high compared to DSG2-low melanomas." (PMID 27340778, 2016). "Thus, amongst a panel of 41 additional human melanoma cell lines, DSG2 was broadly and heterogeneously expressed while the other desmosomal cadherins showed negligible expression." (PMID 27340778, 2016). "There are conflicting reports regarding DSG2 expression in patient melanomas." (PMID 27340778, 2016). "Taken together, these findings substantiate our hypothesis that Dsg2 knockdown leading to an upregulation of SgII and SN promotes migration of melanoma cells." (PMID 24558503, 2014). "These discrepancies may indicate that the impact of Dsg2 on proliferation is cell type- or context-dependent, all the more as distribution and complex formation of Dsg2 in epithelial cells and melanoma cells is completely different." (PMID 24558503, 2014). "Moreover the exact subcellular distribution of Dsg2 in these tumors remains to be uncovered, all the more as they do not contain desmosomes or desmosome-like structures, and the prognostic value of Dsg2 in melanomas remains to be determined." (PMID 24558503, 2014). "Our findings suggest that overproduction of SN upon Dsg2 depletion may represent a novel mechanism triggering melanoma cell migration." (PMID 24558503, 2014). "In summary, we show that desmoglein 2 expression attenuates migration of melanoma cells." (PMID 24558503, 2014). "Finally, we emphasize the occurrence of the desmosomal transmembrane glycoprotein, desmoglein Dsg2, out of the context of any junction as dispersed cell surface molecules in certain types of melanoma cells and melanocytes." (PMID 20671973, 2010). "Similarly, melanoma cell proliferation was unaffected by DSG2 knockdown." (PMID 27340778, 2016). "Moreover, the expression of DSG2 in melanoma might represent re-activation of an embryonic pathway that is suppressed in normal adult melanocytes." (PMID 27340778, 2016). "Previous studies have shown that DSG2 can regulate several biological processes in addition to its canonical function in desmosomal adhesion, including proliferation and cell death in epithelial cells, actin cytoskeletal architecture in ECs and melanoma cell migration." (PMID 27340778, 2016). "Furthermore, studies by our laboratory and others have demonstrated a role for DSG2 in regulating multiple aspects of endothelial cell biology, including barrier function and angiogenic activity, and in promoting vasculogenic mimicry activity of human melanoma cells." (PMID 34245117, 2022). "Thus it was with great surprise when we noted the occurrence of Dsg2 molecules dispersed over large portions of the surface membrane of certain cultures of human melanocytes or neval cells as well as on surfaces of a subtype of melanoma cells in situ and in culture." (PMID 20671973, 2010).
melanoma (continued). "Polyclonal Dsg2 antibody and the immunogenic epitope derived from EC2 domain suppress EMT and invasion of human melanoma, breast cancer, and prostate cancer cells, consistent with the observation that Dsg2 exhibits a non-adhesive function for cell migration and morphogenesis." (PMID 30790141, 2019). "Mechanistic studies revealed that DSG2 regulates adhesion and cell-cell interactions during tube formation, but does not control melanoma cell viability, proliferation or motility." (PMID 27340778, 2016). "And while DSG2 has been suggested to regulate the actin cytoskeleton in ECs, DSG2 knockdown did not have a similar effect in cultured melanoma cells." (PMID 27340778, 2016). "We have previously shown that a subtype of melanoma cells express the desmosomal cadherin desmoglein 2 as non-junction-bound cell surface protein in addition to classical cadherins." (PMID 24558503, 2014). "By contrast, neither our BrdU incorporation experiments nor our MTT assays supported involvement of Dsg2 in melanoma cell proliferation." (PMID 24558503, 2014). "Many of the non-desmosomal functions ascribed to DSG2 in various cell types could be expected to impact on the VM capacity of melanoma cells." (PMID 27340778, 2016). "Reports also document ‘non-junction-bound’ DSG2 on epithelial cells and cancer cells where it provides additional biological roles including regulation of apoptosis, proliferation and vasculogenic mimicry in melanoma." (PMID 27338829, 2016). "Despite the lack of other desmosomal cadherins, DSG2 may nevertheless mediate melanoma cell adhesion in a desmosome-independent context, a possibility which has been previously proposed but not rigorously tested." (PMID 27340778, 2016). "Finally, using two different approaches, we did not detect any change in melanoma cell migration following DSG2 knockdown, which is in contrast to a previous study for reasons that are presently unclear." (PMID 27340778, 2016). "Moreover, it will be interesting to study the occurrence, the amounts and the regulation of SgII and SN in other melanoma cell lines, including Dsg2-negative ones, and to correlate findings to their migratory capacity." (PMID 24558503, 2014). "To evaluate the impact of Dsg2 on invasive properties of melanoma cells independent of their migratory capacities, we used a TEER breakdown assay, which allows to measure cancer cell-monolayer violation at the very beginning of invasion with a very high sensitivity." (PMID 24558503, 2014). "By contrast, intercellular junctions between melanoma were mostly Dsg2-negative, except in two primary melanomas and one melanoma metastasis in which Dsg2-positive immunoreactions appeared to be focally enhanced at cell-cell contacts of 5-10% of the tumor cells." (PMID 24558503, 2014). "However, in melanoma cells Dsg2 is neither assembled into any cell junction nor found in junctional protein complexes except for plakoglobin but dispersed diffusely over the cell surface." (PMID 24558503, 2014). "Interestingly, although DSG2 clearly plays an important role in regulating VM, it is not absolutely required for this process, as we have identified several melanoma cell lines which lack DSG2 expression and yet can still form tubes on Matrigel (unpublished findings)." (PMID 27340778, 2016). "Together, these data reveal that DSG2 (distinct from other desmosomal cadherins) is induced de novo in a subset of human melanomas and can be expressed throughout the disease course, but may be subject to temporal and spatial regulation within individual patients." (PMID 27340778, 2016). "Thus, using two different assays, we could not reproduce the reported increase in melanoma cell migration upon DSG2 knockdown." (PMID 27340778, 2016). "Therefore, Dsg2 appears to affect neither proliferation nor viability of melanoma cells." (PMID 24558503, 2014).